LINC00992 (long independently transcribed non-coding RNA 992)
Synonyms: GT3-INCP; ERINA; LOC124900192
Gene: Long non-coding RNA gene on chromosome 5 (117,415,509 to 117,577,694, forward strand). Ensembl gene ENSG00000248663.
Diseases named in the same sentence as LINC00992 in open-access papers:
LINC00992 is named in the same sentence as 5 diseases in open-access papers, as found by Europe PMC text mining. Sharing a sentence is not in itself a finding about the gene and the disease. The quoted sentences say what the papers report.
breast carcinoma (7 papers, 2021 to 2025). "Among these, LINC00992 has been linked to poor outcomes in luminal breast cancer and is responsible for producing the GATA3-interacting cryptic protein (GT3-INCP)." (PMID 39333489, 2024). "The predicting value of 11 sARLNRs (U62317.4, LINC01016, LINC02166, C6orf99, LINC00992, BAIAP2-DT, AC245297.3, AC090912.1, Z68871.1, LINC00578, and LINC01871) was also identified in breast cancer." (PMID 34414116, 2021). "In conclusion, we identified a novel autophagy‐related prognostic risk model consisting of 11 lncRNAs (U62317.4, LINC01016, LINC02166, C6orf99, LINC00992, BAIAP2‐DT, AC245297.3, AC090912.1, Z68871.1, LINC00578 and LINC01871) in breast cancer." (PMID 33216456, 2021).
prostate adenocarcinoma (1 paper, 2020). "As a result, LINC00992 was considerably upregulated in PRAD (prostate adenocarcinoma) tissues relative to normal ones." (PMID 32781986, 2020).
prostate carcinoma (1 paper, 2020). A carcinoma that arises from epithelial cells of the prostate gland. "As expected, a declined proportion of EdU positive cells was observed after knocking down LINC00992, suggesting the suppressive effect of LINC00992 deficiency on prostate cancer cell proliferation." (PMID 32781986, 2020). "Moreover, clinical data showed that higher expression of LINC00992 in prostate cancer patients was associated with lower survival rate." (PMID 32781986, 2020). "Our study for the first time uncovered that LINC00992 located mainly in the cytoplasm of prostate cancer cells." (PMID 32781986, 2020). "LINC00992 competitively bound with miR-3935 to elevate GOLM1 expression and therefore facilitate the oncogenic phenotypes of prostate cancer cells, implying a potential LINC00992-targeted therapy for prostate cancer." (PMID 32781986, 2020). "After detecting LINC00992 expression in tissue samples obtained from patients with prostate cancer, we observed that LINC00992 expression was higher in prostate cancer tissues than that in peri-tumor tissues." (PMID 32781986, 2020). "Despite that, no previous study has given a comprehensive explanation about the precise function or detailed mechanism of LINC00992 in prostate cancer." (PMID 32781986, 2020). "Taken together, LINC00992 promoted the tumorigenesis of prostate cancer through upregulating GOLM1 expression." (PMID 32781986, 2020). "Before exploring LINC00992-mediated mechanism in prostate cancer, herein we firstly discovered its subcellular distribution in prostate cancer cells with both aids from online prediction tool (LncLocator) and experimental data (FISH and RNA isolation of nuclear and cytoplasmic fractions)." (PMID 32781986, 2020). "As documented in cancer-related literatures, LINC00992 expression is associated with cancer progression, whereas its function in tumors including prostate cancer has not been characterized yet." (PMID 32781986, 2020). "Consequently, higher level of LINC00992 was exhibited in prostate cancer cells than that in RWPE-1 cells, which was completely consistent with the result presented in previous discovery." (PMID 32781986, 2020). "Data from GEPIA database suggested LINC00992 expression in prostate cancer tissues." (PMID 32781986, 2020). "Nevertheless, whether LINC00992 could exert its functions in prostate cancer via its sponging role of certain miRNA remains unknown." (PMID 32781986, 2020). "LINC00992 exerted facilitating functions in prostate cancer cell proliferation and migration." (PMID 32781986, 2020). "In our work, LINC00992 was revealed to be highly expressed in prostate cancer tissues and cells, but unlike former investigations, our study gave a precise explanation about its role in prostate cancer." (PMID 32781986, 2020). "Furthermore, LINC00992 expression in the prostate cancer cells and RWPE-1 cells was evaluated by qRT-PCR." (PMID 32781986, 2020). "All these data elucidated that LINC00992 could facilitate cell proliferation and migration whereas suppress cell apoptosis in prostate cancer." (PMID 32781986, 2020). "LINC00992 expression pattern in prostate cancer was acquired from online GEPIA database." (PMID 32781986, 2020). "Likewise, FISH assay and RNA isolation of nuclear and cytoplasmic fractions further verified the abundance of LINC00992 in the cytoplasm of prostate cancer cells, highlighting a post-transcriptional control of LINC00992 in such cells." (PMID 32781986, 2020). "Hence, we speculated that LINC00992 might act as a ceRNA in prostate cancer regulation." (PMID 32781986, 2020). "Mechanically, LINC00992 interacted with and negatively regulated miR-3935 to elevate GOLM1 expression in prostate cancer cells." (PMID 32781986, 2020).
cancer (4 papers, 2018 to 2024). A tumor composed of atypical neoplastic, often pleomorphic cells that invade other tissues. "For example, the expression of LINC00992 in primary tumors increases along with the disease progression and correlates with poor patient survivals in multiple cancer types that are routinely treated with chemotherapy." (PMID 30093685, 2018).
tumor (3 papers, 2020 to 2023). "The LINC00992-encoded polypeptide GT3-INCP was upregulated in ER+ BC and drove tumor growth." (PMID 36856112, 2023). "We confirmed the in vivo tumor-promoting function of an unannotated protein, GATA3-interacting cryptic protein (GT3-INCP) encoded by LINC00992, the expression of which was associated with poor prognosis in luminal tumors." (PMID 36856111, 2023). "Likewise, LINC00992 depletion restrained tumor growth in vivo was offset by enhanced GOLM1 expression." (PMID 32781986, 2020).